LOXL2 (lysyl oxidase like 2)
Diseases named in the same sentence as LOXL2 in open-access papers (continued):
Sharing a sentence is not in itself a finding about the gene and the disease.
breast carcinoma (continued). "The novel findings in our study demonstrate that the proinflammatory cytokine OSM promotes the expression of LOXL2 in breast cancer cells, which significantly impacts collagen I fiber crosslinking, fiber alignment, and invasion." (PMID 34011405, 2021). "LOX and LOXL2 inhibition have thus been suggested as a promising strategy to prevent metastasis and invasion of breast cancer." (PMID 33669630, 2021). "Expression of LOXL2 in breast cancer cells is positively correlated with the invasive potential of the breast tumor cells." (PMID 34011405, 2021). "Conversely, breast cancer tissues show increased LOXL2 expression, located intracellularly in the cytoplasm and cell nuclei, and extracellularly in the ECM." (PMID 33669630, 2021). "These two LOX/LOXL2 inhibitors reduced the in vitro 2D and 3D proliferation of the breast cancer cell line MDA-MB-231 in a dose-dependent way." (PMID 33669630, 2021). "The discovery of PXS-S2A established the basis for dissecting the functional role of LOXL2 in the progression of solid tumors such as breast cancer." (PMID 33669630, 2021). "The researchers found differential LOXL2 concentrations in patients with breast cancer (≈ 2.7 μM in blood; ≈ 40 μM in urine), when compared to the cancer-free individuals (≈ 0.6 μM in blood; ≈ 25 μM in urine)." (PMID 33669630, 2021). "Regarding patients with breast cancer, serum LOXL2 levels were elevated by 218% compared to healthy controls." (PMID 33669630, 2021). "LOXL2 was shown to promote an EMT of breast cancer cells resulting in invasive and stem-like properties of the cancer cells." (PMID 34011405, 2021). "Among the different LOX enzymes, this review gives particular emphasis to the human LOXL2 (hLOXL2) due to the importance of this particular isoform to breast cancer progression." (PMID 33669630, 2021). "In breast cancer, LOXL2 contributes to cancer progression through up-regulating the expression of vascular endothelial growth factor." (PMID 34308761, 2021). "PXS-S1A/C and PXS-5382A, which inhibit LOXL2, have also been shown to delay tumour growth and reduce collagen accumulation in orthotopic models of breast cancer, and in orthotopic LY2 oral cancer models, respectively." (PMID 33513979, 2021). "Inhibiting NADPH oxidase 4 attenuated lymphangiogenesis in breast cancer, and the knockdown of lysyl oxidase-like protein 2 (LOXL2) suppressed lymphangiogenesis and lymph nodes metastases." (PMID 35054174, 2021). "We observed a moderate to weak, yet significant, positive Pearson correlation of 0.263 (p = 6.97 × 10-20) between OSMR expression and LOXL2 expression in breast cancer patients." (PMID 34011405, 2021). "Transgenic mouse models of PyMT-induced breast cancer were used to explore the role of LOXL2 in driving breast cancer metastases." (PMID 33669630, 2021). "Overall, this work contextualizes and explores the importance of LOXL2 inhibition as a promising novel complementary and effective therapeutic approach for breast cancer treatment." (PMID 33669630, 2021). "Previously, our lab demonstrated a role for LOXL2 in mediating morphological changes to collagen fibers in vitro and in vivo in a breast cancer model." (PMID 32296422, 2020). "LOXL2 has accumulated numerous reports that document its role in cancer formation and proliferation of breast cancer." (PMID 32064050, 2020). "In this work, we found that several TNBC cell lines and PDXs express high levels of LOXL2 as compared with those of the luminal breast cancer subtype." (PMID 31462706, 2020). "Intriguingly, mesenchymal triple-negative breast cancer (TNBC) cell lines as well as breast cancer patient-derived xenografts (PDXs) had high H3K4ox levels that correlated with high LOXL2 expression, as compared with other subtypes." (PMID 31462706, 2020). "Expression of LOXL2 in MCF-7 breast cancer cells colonizing to the lung induced their transition from dormancy to metastatic outgrowth." (PMID 31817646, 2019).
breast carcinoma (continued). "In breast cancer, LOXL2 inhibition showed anti-tumor effects in reducing tumor size and angiogenesis." (PMID 31106200, 2019). "Beside the action of LOX, crosslinking of collagen by secreted LOXL2 has been shown to contribute to breast cancer progression by promoting integrin signaling via the focal adhesion kinase (FAK)." (PMID 29755969, 2018). "The LOXL2 association with EMT regulatory transcription factor Snail1 stabilizes Snail1 expression, promoting breast cancer cells to undergo EMT." (PMID 29881724, 2018). "Selected literature references with regards to involvement of lysyl oxidase isoforms LOX and LOXL2 in various kinds of tumors in addition to breast cancer and melanoma." (PMID 29755969, 2018). "ER+ dormant breast cancer cells expressing lysyl oxidase homolog 2 (LOXL2) acquire stem-like characteristics that depend on epithelial mesenchymal programs to mediate exit from dormancy." (PMID 30119678, 2018). "For instance, a recent study considering a mouse model a breast cancer xenografts demonstrated the benefit of disrupting lysyl oxidase like 2 (LOXL2)-mediated ECM fibril alignment." (PMID 28794454, 2017). "Like LOX, LOXL2 was shown to promote invasive/metastatic phenotypes in breast cancer cells which was explained by altered LOXL2 protein processing and localization." (PMID 28425924, 2017). "Our data provides the first evidence to support a role for LOXL2 specific small molecule inhibitors as a potential therapy in breast cancer." (PMID 28199967, 2017). "Previous research from both our lab and other labs has identified an important role for LOXL2 in mediating breast cancer progression, and highlighted its therapeutic value." (PMID 28199967, 2017). "Here we tested the anti-tumor properties of two generations of novel small molecule LOXL2 inhibitor in the MDA-MB-231 human model of breast cancer." (PMID 28199967, 2017). "Dual LOX / LOXL2 inhibition (PXS-S1A) showed a greater degree of inhibition supporting previous studies on the role of LOX in breast cancer primary tumor growth." (PMID 28199967, 2017). "Here, we report the anti-tumor effects of the first selective LOXL2 small molecule inhibitors in models of human breast cancer." (PMID 28199967, 2017). "Our objective was to evaluate the efficacy of two generations of novel LOXL2 inhibitor in both in vitro and in vivo models of human breast cancer in order to determine the functional role of LOXL2 in breast cancer progression." (PMID 28199967, 2017). "Our data show that both LOX and LOXL2 play a significant role in 2D and 3D proliferation of breast cancer cells." (PMID 28199967, 2017). "To confirm the effects of small molecule mediated LOXL2 inhibition in breast cancer cells, we stably knocked down LOXL2 in the MDA-MB-231 cells using separate shRNA constructs." (PMID 28199967, 2017). "In fact, the ratio of LOXL2 positivity in early-stage pancreatic cancer was higher than that in breast cancer, renal cell carcinoma, and stomach cancer." (PMID 27285767, 2016). "Recently, intracellular expression of Loxl2 in a breast cancer model stimulated tumour invasiveness." (PMID 26804196, 2016). "In recent years, research focus has shifted toward the LOXL2 isoform owing to its elevated expression in patients with breast cancer." (PMID 26265048, 2015). "Consistent with this, other studies found LOXL2 protein levels to be higher in poorly differentiated breast carcinomas, and elevated LOXL2 mRNA was observed in invasive and metastatic breast cancer cell lines." (PMID 23971878, 2013). "We have inhibited the expression of Loxl2 in several types of breast cancer cells and in cells derived from fibrosarcoma using a shRNA species specific for Loxl2 which strongly inhibits Loxl2 expression." (PMID 19948022, 2009).
breast carcinoma (continued). "However, the following studies have found that LOXL2 was highly expressed in breast cancer, colorectal cancer, esophageal cancer, bile duct cancer, liver cancer, pancreatic cancer and gastric cancer, and was closely associated with metastasis and prognosis." (PMID 41281746, 2025). "In addition, LOXL2 can inhibit E-cadherin expression by binding and oxidizing H3K4me3 in breast cancer cells." (PMID 41281746, 2025). "In addition to small-molecule inhibitors, another LOXL2 inhibitor is the patented de primary amino-containing diazocynonane compound, which was tested in a transgenic mouse model of breast cancer and shown to availably reduce lung metastasis formation." (PMID 40211368, 2025). "LOXL2 also increases the expression and secretion of prolymphangiogenic factors in fibroblasts in breast cancer in a HIF-1α-dependent manner, stimulating the Akt-Snail and Erk signalling pathways to enhance lymphangiogenesis and lymph node metastasis in breast tumours." (PMID 39247609, 2024). "Importantly, there have been reports of increased LOXL2 expression in breast cancer cells, and especially in TNBC cells." (PMID 38672570, 2024). "Notably, LOXL2 is produced not only by tumour cells but also by stromal cells, highlighting its diverse involvement in the spread of breast cancer." (PMID 39247609, 2024). "Additionally, LOXL2 shows promise in the detection of various phases of breast cancer, from initial to advanced stages." (PMID 39247609, 2024). "Inhibition of LOXL2 through genetic method (knockdown of the LOXL2 gene), chemical intervention (using D-penicillamine), or antibody-based targeting of LOXL2 has been shown to markedly diminish the development of distant metastases in an orthotopic model of immunocompromised breast cancer." (PMID 39247609, 2024). "The results showed that LOX and LOXL2 are critical for the growth of breast cancer cells." (PMID 38672570, 2024). "Moreover, LOXL2 has been identified as a potential prognostic indicator for breast cancer, and is capable of distinguishing between different stages of the disease, from carcinoma in situ to invasive cancer." (PMID 39247609, 2024). "Moreover, a significant proportion (60%) of basal-like breast cancer cells exhibit high LOXL2 expression." (PMID 39247609, 2024). "Furthermore, chemical or genetic inhibition of LOXL2 significantly reduces metastasis in orthotopic and transgenic breast cancer models." (PMID 38238542, 2024). "By taking advantage of the CPTAC proteomics dataset, we stratified breast cancer samples into different breast cancer subtypes and observed that LOXL2 protein levels were significantly increased in each of them, whereas BRD4 only showed a mild increase in TNBC." (PMID 37937685, 2023). "Anti-LOXL2 treatment is sufficient to suppress tumor progression in breast cancer." (PMID 36906534, 2023). "The nuclear action of LOXL2 in the invasion and tumorigenesis of breast cancer cells is also mediated, at least in part, through the upregulation of the receptor activity-modifying protein 3 (RAMP3) gene, although the implication of RAMP3 in EMT has not been investigated yet." (PMID 37762708, 2023). "In breast cancer cells, secreted LOXL2 enhances lymphatic endothelial cell invasion through AKT and ERK signalling and stimulates fibroblasts to secrete pro-lymphangiogenic factors such as vascular endothelial growth factor C (VEGF-C) and stromal cell-derived factor 1 (SDF-1α)." (PMID 37762708, 2023). "LOXL2, which is strongly induced by hypoxia condition, has been identified to exert its protumor effects by promoting tumor progression in various cancers, including breast cancer, colorectal cancer, cervical cancer, and LUAD." (PMID 36276289, 2022). "Thus, dormant MCF-7 breast cancer cells colonizing the lung remain dormant, but transition to metastatic growth following LOXL2 expression." (PMID 35682926, 2022).
breast carcinoma (continued). "In tumor cells, LOXL2 can upregulate human epidermal growth factor receptor 2 (ErbB2) expression through the production of reactive oxygen species (ROS), and ErbB2-positive breast cancer patients with high LOXL2 expression have poorer OS and MFS." (PMID 36293126, 2022). "Consequently, inhibition of these enzymes and, in particular of LOXL2, has been suggested as a therapeutic strategy to prevent breast cancer metastasis." (PMID 35800439, 2022). "Some early preclinical success in this has demonstrated the detection of LOXL2 within both murine and human blood samples of breast cancer patients, where hydrogen peroxide release, a product of LOX family activity, was detected via the use of a gold-based electrochemical biosensor." (PMID 33513979, 2021). "Therefore, the possible therapeutic strategies for inhibiting LOXL2 in breast cancer will be more efficient if intracellular LOXL2 is blocked." (PMID 33669630, 2021). "Our lab, and others, have previously analyzed OncomineTM and other breast cancer patient databases demonstrating a correlation between reduced recurrence-free survival (RFS) of breast cancer patients with higher expression of LOXL2 and reduced survival rates with higher expression of OSM/OSMR." (PMID 34011405, 2021). "Inhibition of the collagen-crosslinking lysyl oxidase (LOX) family in mice decreased fibrosis as well as tumor incidence and tumor size in a mouse model, and high lysyl oxidase-like 2 (LOXL2) expression correlates with low overall and metastasis-free survival in breast cancer patients." (PMID 33534863, 2021). "The importance of GRP78’s interaction with LOXL2 (lysyl oxidase-like 2) was established for EMT induction in breast cancer cells; this interaction results in stimulation of the IRE1/XBP1 signaling pathway followed by expression of SNAI1, SNAI2, ZEB2, and TCF3 being the EMT drivers." (PMID 32268506, 2020). "We found that reducing H3K4ox levels via LOXL2 depletion led to chromatin decondensation, triggered DDR activation, and induced cell cycle arrest, suggesting that LOXL2 inhibition could be interesting as a breast cancer treatment." (PMID 31462706, 2020). "LOXL2 is overexpressed in many tumors, and especially in breast cancers." (PMID 31462706, 2020). "The overexpression of LOXL2 played a tumor‐promoting role and indicated poor prognosis in esophageal squamous cell carcinoma, hepatocellular carcinoma, lung carcinoma, gastric carcinoma, and breast carcinoma." (PMID 33058284, 2020). "Interestingly, in mice bearing aggressive breast cancer, anti-LOXL2 monoclonal antibody AB0023 exhibited potent inhibitory effects in activated fibroblast as suggested by an 88% reduction of α-SMA+ cells by immunohistochemistry (IHC) after AB0023 treatment." (PMID 31106200, 2019). "Similarly, LOXL2 upregulation has been described in human cancers, including squamous cell carcinomas, breast cancer and pancreatic ductal adenocarcinoma." (PMID 31130685, 2019). "Similarly, next generation LOXL2 inhibitors are effective in pre-clinical models of gastric and breast cancer as well as lung and liver fibrosis models, with targeted therapeutics against LOXL2 currently undergoing Phase I/II testing." (PMID 31061140, 2019). "In conclusion, we propose that, at least in laryngeal squamous cell carcinomas and basal-like breast carcinomas, the observed intracellular LOXL2 staining pattern corresponds to protein temporally retained in the ER that activates the IRE1-XBP1 and PERK branches of the UPR." (PMID 28332555, 2017). "We confirmed a functional role for LOXL2 activity in the progression of primary breast cancer." (PMID 28199967, 2017). "In addition to SNAIL1 effects, LOXL2 influences expression of SPARC and the extracellular proteins TIMP1 and MMP9; in fact, LOXL2 was noted as prognostic factor in breast cancer." (PMID 28425924, 2017).
breast carcinoma (continued). "Therefore our data show that early inhibition of LOXL2-mediated angiogenesis in developing primary breast cancer leads to the decrease in the growth of the primary tumor." (PMID 28199967, 2017). "Remarkably, perinuclear/cytoplasmic accumulation of LOXL2 is a poor prognosis marker of squamous cell carcinomas and is associated to basal breast cancer metastasis by mechanisms no yet fully understood." (PMID 28332555, 2017). "LOXL2 activity in basal-like carcinoma cells were found to affect tight junction and cell polarity complexes by a mechanism which involves downregulation of involved genes and, LOXL2 is required for cell invasion, tumor growth, and lung metastasis of basal-like breast carcinoma cells." (PMID 28425924, 2017). "Interestingly, analysis of breast cancer relapse free survival data set revealed that increase in LOXL2 expression is correlated with increase in the EMT/CSC markers fibronectin and Slug." (PMID 27655685, 2016). "Overall, our results suggest that determining LOXL2 expression levels may serve as a good prognostic marker for the RFS of breast cancer patients." (PMID 27655685, 2016). "Moreover, LOXL2 expression has been demonstrated to clinically correlate with metastasis and decreased survival of breast cancer patients." (PMID 27655685, 2016). "Moreover, we showed that LOXL2 expression correlates with metastasis and poor survival in ErbB2-positive breast cancer patients." (PMID 23971878, 2013). "A retrospective study on a previously published breast cancer patient dataset was carried out by using Disease Specific Genomic Analysis (DSGA) to investigate the correlation of LOXL2 mRNA expression level with metastasis and survival of ErbB2-positive breast cancer patients." (PMID 23971878, 2013). "Finally, we found LOXL2 expression to be correlated with decreased overall survival and metastasis-free survival in breast cancer patients with ErbB2-positive tumors." (PMID 23971878, 2013). "LOXL2 may also be a beneficial marker for breast cancer patients that could benefit most from anti-ErbB2 therapy." (PMID 23971878, 2013). "Finally, we showed that high LOXL2 expression correlates with poor prognosis in ErbB2-positive breast cancer patients, demonstrating a strong link between LOXL2 and ErbB2 and aggressive cell behavior." (PMID 23971878, 2013). "Our results link LOXL2 to RBPs’ modulation in breast cancer; thus, using LOXL2 inhibitors in combination with RBP inhibitors may provide a more effective therapeutic strategy for treating breast cancer, as well as circumventing potential issues associated with targeting LOXL2 alone." (PMID 37298909, 2023). "LOXL2, a copper-containing enzyme, is closely related to reduced survival time and poor prognosis since it promotes the proliferation, migration, invasion, and metastasis of numerous types of cancers, including breast cancer, lung cancer, colon cancer, and liver cancer." (PMID 36620542, 2022). "In addition, LOXL2 expression in dormant tumor cells (DTC) induces EMT and contributes to the acquisition of a cancer stem cell (CSC)-like phenotype, thereby causing the recurrence of breast cancer." (PMID 36293126, 2022). "A possible mechanism through which this may occur is the creation by LOXL2 of a collagen scaffold that helps disseminate cancer cells; copper depletion decreases collagen cross-linking, as measured by LOXL2 levels, thus preventing breast carcinoma metastasis." (PMID 36620542, 2022). "Interestingly, LOXL2 facilitates cancer cell dedifferentiation, migration, and metastasis in a variety of desmoplastic cancer models (e.g., breast cancer, PDAC, muscle-derived rhabdomyosarcoma) but exhibits diverse effects on ECM organization, even within specific cancer types." (PMID 35804902, 2022). "LOXL2 may be a promising therapeutic target for preventing invasive/metastatic of breast cancer." (PMID 29728125, 2018). "Firstly, we observed whether escin Ia inhibited LOXL2 expression in breast cancer cells." (PMID 27008697, 2016).